EXOC3L1 (exocyst complex component 3 like 1)
Description:
As part of the exocyst, may play a role in regulated exocytosis of insulin granules.
Synonyms: EXOC3L; FLJ35539; FLJ35587
Tractability: Antibody: the Human Protein Atlas places it where antibodies can reach.
Gene: Protein-coding gene on chromosome 16 (67,184,314 to 67,190,242, reverse strand). Ensembl gene ENSG00000179044.
Subcellular location: Cytoplasmic vesicle, secretory vesicle
Subcellular location (Human Protein Atlas): Plasma membrane; Vesicles
Gene Ontology:
Molecular function: protein binding; SNARE binding
Biological process: exocyst localization; exocytosis; peptide hormone secretion
Cellular component: exocyst; secretory granule; transport vesicle
Genetic constraint (gnomAD): Loss-of-function variants: 81 observed, 83.28 expected, observed/expected ratio (o/e) 0.97, 90% interval 0.81 to 1.17. The upper end of that interval is the gene's LOEUF score, 1.17, which puts it in group 5 of 6, group 1 being the genes least tolerant of losing a copy. Missense variants: 945 observed, 939.74 expected, observed/expected ratio (o/e) 1.01, 90% interval 0.95 to 1.06. Synonymous variants: 433 observed, 429.87 expected, observed/expected ratio (o/e) 1.01, 90% interval 0.93 to 1.09.
Homologues: Orthologues: chimpanzee EXOC3L1 (99% identical), macaque EXOC3L1 (96% identical), rabbit EXOC3L1 (82% identical), dog EXOC3L1 (81% identical), pig EXOC3L1 (81% identical), rat Exoc3l1 (79% identical), mouse Exoc3l (78% identical), guinea pig EXOC3L1 (73% identical), tropical clawed frog exoc3l1 (38% identical), zebrafish exoc3l1 (37% identical). Paralogues in human: EXOC3 (28% identical), EXOC3L2 (22% identical), EXOC3L4 (19% identical), TNFAIP2 (19% identical).
Diseases named in the same sentence as EXOC3L1 in open-access papers:
EXOC3L1 is named in the same sentence as 7 diseases in open-access papers, as found by Europe PMC text mining. Sharing a sentence is not in itself a finding about the gene and the disease. The quoted sentences say what the papers report.
brain injury (1 paper, 2022). Acute and chronic (see also brain INJURIES, CHRONIC) injuries to the brain, including the cerebral hemispheres, CEREBELLUM, and brain STEM. "Up to the present day, limited studies have shown that EXOC3L1 were involved in the regulation of insulin secretion, protein secretion after traumatic brain injury, spontaneous induction of apoptosis, and high-density lipoprotein concentration, but the exact function of EXOC3L1 remains unclear." (PMID 36479245, 2022).
lung squamous cell carcinoma (1 paper, 2022). "Furthermore, representative cancers kidney renal clear cell carcinoma (KIRC) and lung squamous cell carcinoma (LUSC) with a sample size larger than 500 were selected to construct nomogram models to confirm the prognostic value of EXOC3L1 in cancers." (PMID 36479245, 2022).
cancer (1 paper, 2022). A tumor composed of atypical neoplastic, often pleomorphic cells that invade other tissues. "In order to survey the prognostic assessment value of EXOC3L1 in pan-cancer, Kaplan-Meier survival analysis was carried out to evaluate the relationship between EXOC3L1 expression and clinical outcomes." (PMID 36479245, 2022). "To further investigate the effect of EXOC3L1 expression on the prognosis of specific cancers, we performed univariate Cox regression analysis for OS in six tumors in which EXOC3L1 can affect the prognosis." (PMID 36479245, 2022). "Collectively, EXOC3L1 plays multifaceted roles in pan-cancer, which can affect the prognosis and immune microenvironment of specific cancers, and provides a novel biomarker and a potential therapeutic target." (PMID 36479245, 2022). "Our research aims to investigate the roles of EXOC3L1 in pan-cancer, its correlation with the immune microenvironment, and to preliminarily explore the mechanism of EXOC3L1 in tumors." (PMID 36479245, 2022). "In order to study the relationship between EXOC3L1 and immune microenvironment in pan-cancer, the correlation between EXOC3L1 expression and immune cells in pan-cancer was carried out by using the GEPIA2 database." (PMID 36479245, 2022). "In order to clarify the expression of EXOC3L1 in pan-cancer, the uniformed TCGA_GTEx data collected from the UCSC were analyzed." (PMID 36479245, 2022). "There are no reports on the study of EXOC3L1 in tumors so far, and the roles of EXOC3L1 in pan-cancer are far from clear, making it necessary to explore the role of EXOC3L1 in pan-cancer." (PMID 36479245, 2022). "In the present study, we aimed to investigate the roles of EXOC3L1 in pan-cancer, and the data was downloaded from of the University of California Santa Cruz (UCSC) Xena and the Cancer Genome Atlas (TCGA)." (PMID 36479245, 2022). "Subsequently, Kaplan-Meier analysis was applied to 33 kinds of tumors in TCGA, among the cancers that EXOC3L1 can affect prognosis, clinical correlation analysis and univariate Cox regression analysis were performed." (PMID 36479245, 2022). "Here, for the first time, we explore the relationship between EXOC3L1 and pan-cancer." (PMID 36479245, 2022). "In conclusion, we propose that EXOC3L1 may serve as a potential prognostic biomarker and a promising target for cancer immunotherapy in a variety of cancers." (PMID 36479245, 2022). "Firstly, we were firstly studied the role and mechanism of EXOC3L1 in pan-cancer, and elaborated on expression differences, clinical correlation analysis, survival analysis, immune infiltration analysis, enrichment analysis, etc., which deepened our understanding of EXOC3L1." (PMID 36479245, 2022). "Therefore, the expression status of EXOC3L1 in different cancers is still unclear." (PMID 36479245, 2022). "This study revealed that EXOC3L1 could regulate the immune microenvironment, suggesting that EXOC3L1 may be applied in the development of new-targeted drugs for immunotherapy for some cancers, and benefit a large number of patients suffering cancers." (PMID 36479245, 2022). "Secondly, on the basis of survival analysis, we selected representative cancers KIRC and LUSC with large sample size to further clarify that EXOC3L1 can have an impact on the prognosis of tumors, which makes the conclusions more reliable." (PMID 36479245, 2022). "At present, there is a lack of research on EXOC3L1 in pan-cancer." (PMID 36479245, 2022).
tumor (1 paper, 2022). "We studied the expression differences of EXOC3L1 between normal tissues and tumor tissues of different organs in TCGA_GTEx samples, TCGA samples and TCGA paired samples respectively." (PMID 36479245, 2022). "In order to detect the impact of immune cells infiltration on tumor prognosis, we combined the expression of EXOC3L1 and immune cell infiltration to analyze the effect on tumor OS in GEPIA2." (PMID 36479245, 2022). "Based on these results, we speculate that the effect of immune cells on tumor OS depend on the expression level of EXOC3L1." (PMID 36479245, 2022). "More importantly, in different expression levels of EXOC3L1, immune cells have different effects on tumor prognosis, suggesting that the function of immune cells may depend on the expression level of EXOC3L1." (PMID 36479245, 2022). "Lastly, this study revealed that EXOC3L1 may be involved in tumor development through NOTCH signaling, PI3K-AKT signaling and immune-related pathways, providing directions for future mechanistic studies." (PMID 36479245, 2022). "In addition, enrichment analysis suggested that EXOC3L1 may affect tumor progression through NOTCH signaling pathway, PI3K-AKT and immune-related pathways." (PMID 36479245, 2022). "Meanwhile, the expression of EXOC3L1 in KIRC, KIRP and THCA was correlated with tumor size, lymph node metastasis and pathological stage." (PMID 36479245, 2022). "Thirdly, EXOC3L1 combined with immune cells was used to evaluate the prognosis of tumors, suggesting that the function of immune cells may depend on the expression of EXOC3L1, which further clarified the relationship between EXOC3L1, tumor immune cells and prognosis." (PMID 36479245, 2022). "Further, we studied the protein expression of EXOC3L1 in normal tissues and tumor tissues of different human organs on the HPA, and representative immunohistochemical (IHC) images of normal and tumor tissues of bladder, liver, lung, pancreas, and stomach were extracted." (PMID 36479245, 2022). "In addition, it is worth noting that EXOC3L1 is lowly expressed in LUSC and KIRP, but it plays the role of an oncogene, and is highly expressed in KIRC, but functions as a tumor suppressor gene, this complex relationship requires more experiments to further explain." (PMID 36479245, 2022).
EXOC3L1 also shares sentences with these, for which no sentence is quoted: age-related macular degeneration (1 paper); pancreatic adenocarcinoma (1); thyroid carcinoma (1).